EGF (epidermal growth factor)
Diseases named in the same sentence as EGF in open-access papers (continued):
Sharing a sentence is not in itself a finding about the gene and the disease.
tumor (continued). "The treatment with PYCR1-IN-1 markedly reduced the cell proliferation and the tumor spheroid size induced by the EGFR or TLR agonist in H1975 and HCC827 cells compared with cells treated with EGF or TLR agonists alone (vehicle versus PYCR1-IN-1 in H1975, vehicle versus PYCR1-IN-1 in HCC827)." (PMID 41254241, 2025). "In contrast, EGF expression remained relatively unchanged across all subtypes, including TNBC, and did not demonstrate a significant association with tumor subtype or progression." (PMID 40692603, 2025). "Finally, GFRAL knockdown in tumor cells inhibited GDF15-induced TNF-α and EGF expression, confirming GFRAL as the mediator of GDF15 downstream signaling." (PMID 41035818, 2025). "Von Willebrand Factor (VWF) released by endothelial cells within the tumor vascular system activates platelets, which in turn secrete various angiogenic regulatory factors, including VEGF, epidermal growth factor (EGF), angiopoietin-1, and several anti-angiogenic cytokines." (PMID 39852571, 2025). "The recognition of EZH2, EGF, and AKT1 as pivotal toxicological targets in PCBs-mediated breast carcinogenesis provides critical insights into the molecular pathways through which PCBs facilitate tumor progression." (PMID 40584614, 2025). "This interaction is driven by a CSF-1/EGF paracrine loop, wherein tumor cells secrete CSF-1 (which attracts CSF-1R-expressing macrophages), while macrophages in turn secrete EGF (which attracts EGFR-expressing tumor cells)." (PMID 40646332, 2025). "Tumor cells overproduce osteolytic factors such as PTHrP, IL-11, IL-6, IL-8, vascular endothelial growth factor (VEGF), tumor necrosis factor (TNF), Jagged 1, and epidermal growth factor (EGF)-like ligands." (PMID 40149349, 2025). "Provided the significance of epidermal growth factor (EGF) and focal adhesion kinase (FAK) in promoting tumor proliferation, migration, and angiogenesis of tumors, further investigation displayed a dose and time-dependent significant inhibition of proliferating GBM cells." (PMID 40422257, 2025). "The stronger effect on EGF-induced phosphorylation resulted from blockade of ligand binding and receptor dimerization by the dual epitope EGFR arm as anticipated, while the avidity effect maintained a strong HGF blockade in the tumor cells." (PMID 40452841, 2025). "Furthermore, tumor-derived CSF-1 interacts with epidermal growth factor (EGF) signaling in macrophages, promoting their perivascular accumulation and enabling immune evasion by tumor cells." (PMID 40936918, 2025). "By targeting tumor cells and the C1 SRSF7+ MCs subtype for interactions analysis, we have identified the secretion of AREG ligands by a subtype of C1 SRSF7+ MCs in the EGF signaling pathway that act on the protein receptor EGFR on the membrane of the tumor cells." (PMID 39430754, 2024). "EGF withdrawal significantly reduced the growth of fetal HBTOs by approximately 50% but did not affect the growth of embryonal tumor organoids." (PMID 39567475, 2024). "Recent studies have shown that mast cells infiltrate tumors and tumor microenvironments and release many mediators (e.g., EGF, NGF, PDGF, SCF, angiopoietin, heparin, IL-8, and VEGF), thereby affecting tumor development, tissue remodeling, and tumor-adaptive immune responses." (PMID 39734347, 2024). "In turn, TAM recruit or activate endothelial cells to produce vascular endothelial growth factor A (VEGF-A), epidermal growth factor (EGF), C-X-C motif chemokine ligand 8 (CXCL8), and CXCL12 to promote tumor angiogenesis and continuously provide nutritional support for malignant cells." (PMID 37968342, 2024).
tumor (continued). "Additionally, fibroblasts and mesenchymal cells promote cancer progression by secreting growth factors (VEGF, epidermal growth factor (EGF)), enzymes (MMPs, cyclooxygenase [COX]-2), and signaling molecules that further enhance tumor growth and metastasis." (PMID 39766169, 2024). "The analysis of the relationship between oncogenic drivers and altered signaling pathways in IECs provided evidence of crosstalk among focal adhesion, EGF, MHC, and antigen processing signaling where NOTCH signaling may contribute to tumor immune evasion." (PMID 39456581, 2024). "In the tumor microenvironment, GP73 recycles epidermal growth factor receptor (EGFR) back to the cell-surface under high EGF conditions, or directs it to lysosomes for degradation under low EGF conditions, conserving cellular energy." (PMID 39845976, 2024). "We identified two tumor-specific ligands of Stabilin-1, SPARC and EGF." (PMID 39516356, 2024). "Given the sensitivity of fetal tumor organoids to EGFR inhibitors, we asked whether EGF is essential for organoid culture." (PMID 39567475, 2024). "The violin plot showed the cell-cell interactions while giving the different ligands and receptors in the EGF signaling pathway, and the results showed that C1 SRSF7+ MCs subtype and tumor-cells were mainly contacted with AREG as a ligand and EGFR or ERBB2 as receptors." (PMID 39430754, 2024). "In response to epidermal growth factor signaling, Src-catalyzed PGAM1 Y119 phosphorylation is a prerequisite for PKM2 binding and the subsequent PGAM1 H11 phosphorylation, which constitutes a discrepancy between tumor and normal cells." (PMID 38750259, 2024). "Moreover, it has been described that Epidermal Growth Factor (EGF), through its receptor, induces ROS production via the activation of NOX proteins, thereby activating various signaling pathways involved in tumor cell invasion processes." (PMID 39696702, 2024). "Finally, PL EO can inhibit the EGF/PI3K/Akt pathway inducing apoptosis in cancer cells, leading to inhibition of tumor growth." (PMID 38635559, 2024). "Moreover, we examined the roles of several growth factors and inflammatory cytokines in PDL1 expression HNSCC cells, such as epidermal growth factor (EGF), LPS, IL-6, IL-1β, and TNF-α, commonly in tumor microenvironment." (PMID 38945975, 2024). "Also, MMP-9 expression in the tumor fibroblasts was found to be directly induced by tumor cell-derived TNF-α, EGF, or TGF-β." (PMID 39351229, 2024). "It is crucial to note that therapy-induced tumor cell death promotes the production of growth factors and cytokines, including WNT, EGF, TNF, IL-17, and IL-6, by cells in the TME to promote the survival of remaining tumor cells and play a role in fostering therapy resistance." (PMID 38799159, 2024). "Tumor cells secrete growth factors like TGF-β, EGF, and VEGF, promoting CAF transformation." (PMID 39220640, 2024). "Upon stimulation by TGFβ/EGF, SWAP-70–deficient tumor cells failed to increase the number of focal adhesions and the area that they cover, consistent with the adhesion deficiencies of the mutant cells." (PMID 38760173, 2024). "Tumor angiogenesis relies on blood vessels to provide oxygen and nutrients while eliminating metabolic wastes, a process that is dependent on a variety of factors in the TME such as EGF, VEGF, and so on." (PMID 39691714, 2024). "It releases a variety of cytokines, chemokines, and growth factors that promote tumour cell survival and proliferation, such as prostaglandin E2 (PGE2), CCL17, interleukin-6 (IL-6), tumour necrosis factor-alpha (TNF-α), VEGF, and epidermal growth factor (EGF)." (PMID 38218739, 2024). "PKM2-dependent histone H3 modifications are instrumental in epidermal growth factor (EGF)-induced expression of cyclin D1 and c-Myc, tumor cell proliferation, cell cycle progression, and brain tumorigenesis in its non-metabolic functions of histone modification." (PMID 37196116, 2023).
tumor (continued). "The tumor-promoting microenvironment is generated by stimulating angiogenesis (activation of PI3K pathway via VEGF and EGF), regulating adhesion (changes in composition of integrins), and inflammation (pro-inflammatory cytokines IL6 and IL8 and increased neutrophil to lymphocyte ratio)." (PMID 37445860, 2023). "Epidermal growth factor (EGF) has been shown to induce migration and invasion in tumour cells." (PMID 37038210, 2023). "For example, the negative correlation between patient outcome and level of tumor-associated macrophages (TAM) is reliant upon TAM expression of PDGF, TGF-β, EGF, IL-1, IL-6 and TNF-α, which generates a favorable environment for tumor growth." (PMID 37568595, 2023). "Mutations in these genes lead to sustained activation of downstream signal pathways, causing abnormal cell proliferation independent of epidermal growth factor (EGF) stimulation, ultimately leading to tumor development and continuous progression." (PMID 37631010, 2023). "It was observed that EGF is highly expressed in HCC and positively relates to higher tumor grade." (PMID 37679418, 2023). "EpEX contains two epidermal growth factor (EGF)-like domains, and it may serve as a soluble growth factor to activate EGF receptor (EGFR) in the local tumor microenvironment." (PMID 37543570, 2023). "Mena is an epidermal growth factor (EGF)-responsive cell migration protein which is a member of the Ena/VASP family of actin-binding proteins and is a mediator of cytoskeletal rearrangement, which enhances tumor cell morphology and motility." (PMID 37199172, 2023). "These infiltrated immune cells and solid tumor cells release tumor-progressing cytokines (IL-6, TNF-α, TGF-β), chemokines (CCL2, CCL5, CCL18, CXCL8, CXCL12), and growth factors (EGF, PGF, IGF-1, IGF-2, PDGF) that promote tumor microenvironment immunosuppressive." (PMID 37371075, 2023). "From this viewpoint, a recent report evidenced that TAF produce EGF upon Cet treatment, supporting CRC cell growth and rescuing tumor cells from immunotherapy; thus, CRC-TAF should be considered as targets of therapy to overcome this TME-mediated drug resistance." (PMID 36765569, 2023). "Inflammatory cells release some cytokines, such as COX-2, EGF and VEGF, which are the effectors of tumor tissue promotion; an alteration of immunity cells, both in number and in function, at sites of tumor progression is the generic constituent of the tumor microenvironment." (PMID 37296944, 2023). "EGF production by tumor-infiltrating M2 TAMs within the TME can stimulate the NF-κB, STAT3, EGFR, and extracellular signal-regulated kinase signaling axes in tumor cells, promoting their invasive traits." (PMID 38033495, 2023). "Additionally, the activation of MMPs contributes to tumor growth by activating PAR-1 and by potentiating the release of latent forms of growth factors, such as epidermal growth factor (EGF) and transforming growth factor beta (TGF-β)." (PMID 37686683, 2023). "The infiltrating monocytes, M-MDSCs, and tissue resident macrophages are then educated by the TME and differentiate into TAMs, which in turn produce various types of tumor supportive factors (e.g., EGF and TGF-β) to promote tumor growth, angiogenesis, and metastasis." (PMID 37108657, 2023). "Interestingly, the authors found that EGF secreted by M2-like TAMs inhibited LIMT expression in OC cells, facilitating EMT and tumor progression." (PMID 37373222, 2023). "Moreover, TAMs support tumor growth by producing proangiogenic factors, including VEGFA, EGF, and TGF-β1." (PMID 38008741, 2023). "EGF and EGFR increase tumor cell viability, migration and invasion by PI3K/AKT and MEK/ERK pathway." (PMID 37679666, 2023). "However, we showed that in contrast to tumor-derived HeLa cells, human enMSC retain their proliferation dependence on two EGFR ligands, EGF and TGF-α." (PMID 37686213, 2023).
tumor (continued). "Furthermore, EGF increases the expression of Netrin-4 in the U251MG cell line and prevents tumor cell senescence induced by DNA damage in GBM, hence it is regarded as a protective factor." (PMID 37208656, 2023). "On the other hand, TIS21/BTG2/PC3 can inhibit the degradation of cyclin A and cyclin B1 in G2/M phase when stimulated by epidermal growth factor (EGF) at high concentration, and directly combine with Cdc2, thus hindering cell mitosis and increasing the aging and death of tumor cells." (PMID 37794858, 2023). "Serine proteases can degrade extracellular matrix proteins as well as growth factors such as epidermal growth factor (EGF), fibroblast growth factor-2 (FGF-2) and hepatocyte growth factor/scatter factor (HGF-SF) and are involved in tumour cell invasion, angiogenesis and metastasis." (PMID 37055381, 2023). "Cancer cells can aberrantly express and secrete cytokines and growth factors, such as epidermal growth factor (EGF), VEGF, and fibroblast growth factor (FGF) that act in an autocrine, paracrine, or juxtacrine manner to affect tumor environment and facilitate tumor progression." (PMID 37965134, 2023). "Neutrophils could also produce some secreted factors, such as epidermal growth factor (EGF), hepatocyte growth factor (HGF) and platelet-derived growth factor (PDGF) to sustain tumor proliferation." (PMID 36934105, 2023). "Since we showed that cisplatin decreases the uptake and endocytic trafficking of both classical ligand LDL and tumor-specific ligand EGF but does not significantly affect the SR expression, next we asked which mechanisms are involved in this process." (PMID 36960065, 2023). "Pathogenic H. pylori functions in a multidisciplinary way by upregulating soluble Heparin-binding Epidermal growth factor (HB-EGF) shedding; HB-EGF is vital for tumor progression, metastasis, and is considered a crucial factor in EMT progression especially in the gastric epithelia." (PMID 37609398, 2023). "PI3Kα-driven YAP/TAZ activation, possibly through EGF-EGFR-PI3K or FAK–Src–PI3K activation sequences, is insufficient to promote tumor formation, whereas PI3Kβ-driven YAP/TAZ activation, likely via pertussis toxin-sensitive GPCRs-PI3K activation, allows tumor formation." (PMID 36765741, 2023). "HNSCC tumor cells produce IL-6, CXCL8, and epidermal growth factor (EGF), which improve the survival and angiogenic potential of endothelial cells through the activation of the STAT3/protein kinase B (AKT)/extracellular signal-regulated kinase (ERK) signaling pathways." (PMID 38003931, 2023). "M2-TAMs support tumor growth by producing ornithine, VEGF, EGF, TGF-β, and PGE2." (PMID 38058393, 2023). "Besides, the TGFβ/EGF pathway mediates the nuclear ectopic of PKM2, thereby leading to EMT that promotes tumor metastasis." (PMID 37161591, 2023). "MYL1 promoted HSCC metastasis and correlated with tumor immune infiltration in HNSCC, these functions may be related to the EGF/EGFR signaling pathway." (PMID 37679666, 2023). "In addition, other factors secreted by microglia residing within the GBM, such as the epidermal growth factor (EGF), IL-1β, IL-6, and IL-8, can activate receptors on GBM cells, promoting tumour invasion." (PMID 36675073, 2023). "‐Formation of spheroids composed of macrophages and tumor cells through β2 integrin‐ICAM‐1 interactions.‐Production of EGF by macrophages promoted tumor growth by EFGR signaling in tumor cells, triggering VEGF release by tumor cells and autocrine VEGFR signaling." (PMID 36658699, 2023). "EGF can promote the activation of EGFR, thereby promoting the rapid proliferation of tumor cells." (PMID 36674593, 2023). "CAFs could recruit ITGA5high ascitic tumor cells to form metastatic units, which further sustain ascitic OC cells’ ITGA5 expression by EGF secretion." (PMID 37383389, 2023).
tumor (continued). "Tumor angiogenesis occurs under the influence of fibroblast growth factor (FGF), epidermal growth factor (EGF), vascular endothelial growth factor (VEGF), placental growth factor (PLGF),tumor necrosis factor-alpha (TNFa), platelet-derived growth factor (PDGF) and angiogenin (Ang)." (PMID 35717207, 2022). "It has been reported that 14 of 48 primary UMs and 3 of 14 UM cell lines over-expressed EGFR and that EGFR over-expressing tumours, but not EGFR negative tumours, showed an activated EGF-signature." (PMID 35781872, 2022). "Similarly, hyperactivation of the EGF-EGFR signaling pathway stimulates tumor growth, invasion, and metastatic activity and increases the production of VEGF and FGF in a great variety of tumor cells." (PMID 36079025, 2022). "This method does not separate and digest tumor specimens, but slices the specimens into pieces around 1 mm, and establishes organoids without matrigel and serum, without the addition of EGF and FGF." (PMID 36506083, 2022). "Tumor angiogenesis initiation and development is mainly governed by angiogenic growth factors, such as vascular endothelial growth factor (VEGF), epidermal growth factor (EGF), fibroblast growth factor (FGF), and delta-like 4 (DLL4)." (PMID 35681234, 2022). "Of note, these antibodies did not confer further benefits even when they were combined with MIT (p > 0.05), implying basically independence of PC3 tumor growth on the EGF/EGFR axis, specifically in the absence of stromal cells." (PMID 36202915, 2022). "In contrast, tumor-related macrophages are M2 phenotype macrophages, which synthesize and secrete cytokines, including TGF-β, VEGF, and EGF, to reduce inflammatory response a mediate tissue repair processes, which promote tumor growth, invasion, and metastasis." (PMID 36355531, 2022). "Pro-tumor: Promoting proliferation and invasion of OSCC cells by producing EGF." (PMID 36686729, 2022). "Apart from distinct cells contribute to the HCC metastasis, many kinds of noncellular components of tumor microenvironment have participated in the tumor metastasis, such as TGF-b, vascular endothelial growth factor, epidermal growth factor, and MMPs, E-cadherin, so on." (PMID 36419008, 2022). "However, in the advanced stages, tumor cells secrete other anti-inflammatory cytokines and chemical factors, such as CCL-2 and epidermal growth factor (EGF), leading to the recruitment and conversion of TAMs from the M1 to the M2 phenotype." (PMID 36311793, 2022). "Tumor cells may overexpress specific receptors, such as vascular endothelial growth factor (VEGF), epidermal growth factor (EGF), folic acid (FA), integrin, CD44 (a cell surface glycoprotein), CD13, and prostate-specific membrane antigen." (PMID 35209162, 2022). "In contrast, the expression level of CDH1 and EGF (P-value of < 0.01 and < 0.05, respectively) were significantly lower in the tumor tissues group rather than those found in adjacent normal tissues." (PMID 36284226, 2022). "Eosinophils that infiltrate into tumor environment play both antitumorigenic roles and pro-tumorigenic roles, as they can release interleukins (like IL-10, IL-12 and IFN-γ) or chemokines and growth factors (like EGF, FGF and TGF-β)." (PMID 35903153, 2022). "Further supporting the complexity of crosstalk between IGF-1R and other tyrosine kinase receptor pathways, unclear synergistic actions of EGF, PDGF, TGF-β, and IGF induce stemness, cancer progression and metastasis, drug resistance, and tumor relapse in various cancer types." (PMID 36017326, 2022). "The complex blocked EGF‐mediated activation of EGFR and inhibited tumours more efficiently than when the drug was used alone, whereas the binding between VHH and EGFR endowed the tumour selectivity of the conjugate." (PMID 35593206, 2022). "Various molecules originated from CAFs and tumor-infiltrating immune cells such as TGF-β, FGF, EGF, HGF, and IGF1 along with Hedgehog, Notch, and Wnt signaling pathways could promote EMT." (PMID 35769483, 2022).